MIF (macrophage migration inhibitory factor)
Diseases named in the same sentence as MIF in open-access papers (continued):
Sharing a sentence is not in itself a finding about the gene and the disease.
tumor (continued). "Furthermore, treatment with the dual inhibitor of MIF and DDT, 4-iodo-6-phenylpyrimidine (4-IPP), decreased in vitro proliferation and in vivo tumor growth in a mouse xenograft model." (PMID 32155795, 2020). "In one such report, the effects of MIF on directly suppressing Th1 T cell activation was ruled out using neutralizing anti-MIF antibodies which were found to be unable to attenuate tumor supernatant-induced suppression of T cell proliferation in vitro." (PMID 33324425, 2020). "While this study suggested that CTL-derived MIF directly inhibited anti-tumor CTL activity of primed lymphocytes, a separate finding indicated that tumor-derived MIF is similarly inhibitory to T cell activation and acts by inducing activation-induced T cell death via an IFN-γ-dependent pathway." (PMID 33324425, 2020). "Such a macrophage polarization was also shown by hypoxic tumor exosomes enriched in CCL2, CSF1, TGF-β, macrophage migration inhibitory factor (MIF), ferritin heavy/light chain, endothelial monocyte-activating polypeptide 2 (EMAP2), and leukotriene A-4 hydrolase." (PMID 32499786, 2020). "In hypoxic tissues, such as the tumor microenvironment, there is a reciprocally synergistic relationship between MIF and HIF-1α; hypoxia-driven HIF-1α stabilization and subsequent transcriptional regulation promotes an enhanced expression of MIF." (PMID 33324425, 2020). "MIF-induced CCL4 and MMP9 production in TANs may have tumor autonomous effects by promoting lymphangiogenesis as well as tumor-stromal remodeling." (PMID 33324425, 2020). "MIF has also been suggested to act indirectly as a promoter of GBM progression, via suppression of immunological rejection by activating and protecting the negative regulators, myeloid-derived suppressor cells (MDSCs), within the tumor microenvironment." (PMID 30814573, 2019). "First, we demonstrated the complete lack of MIF in our knockout model and its increased presence during WT tumor development." (PMID 31360118, 2019). "Even though MIF has been shown to have tumor-promoting properties, the absence of MIF from the onset of the tumor in our model promoted the development of larger and more aggressive tumors." (PMID 31360118, 2019). "In the tumor context, it has been documented that M2-polarized macrophages promote pro-tumor functions by production of a large array of growth factors such as COX-2 and MIF for tumor cells, which are essential for tumor proliferation." (PMID 31102112, 2019). "Tumor cells and immunosuppressive cells express or secrete podocalyxin-like protein 1 (PCLP1), activin-a, indoleamine-pyrrole 2,3-dioxygenase (IDO), PGE2, TGF-β, and macrophage migration inhibitory factor (MIF) in the TME to mediate NKG2D downregulation." (PMID 30813924, 2019). "Lack of variation in MIF levels in H. pylori-negative group according to its pathological transformation suggested that MIF partly explains the distinct pathogenesis of H. pylori-positive cancer compared with -negative neoplasm." (PMID 30742638, 2019). "The percentage of T cells in the tumor site was not affected, and we observed the increase of the il-17 relative expression in MIF−/− CRC, indicating that the de novo production of IL-17 by Th17 cells in the tumor was greater than that in WT tumors." (PMID 31360118, 2019). "As discussed in Section 1, intracellular MIF also directly interacts with CSN5 to control the JNK/AP-1 signaling pathway and p27-dependent cell cycle regulation, and inflammatory MIF secretion in endothelial and tumor cells was found to be controlled by CSN5." (PMID 31195722, 2019). "The previous studies have shown that tumor cells produce oxysterol, C-X-C motif chemokine ligand 5 (CXCL5), hyaluronan fragments (HA), granulocyte-macrophage colony stimulating factor (GM-CSF), and macrophage migration inhibitory factor (MIF)." (PMID 30292233, 2018).
tumor (continued). "MIF(-/-) mice also had decreased CD8(+)Tregs and increased CD8-induced tumor cytotoxicity." (PMID 29707160, 2018). "To further understand the mechanism of action of C36L1 on MOs, we evaluated the immunosuppressive and tumor supporting functions of MOs exposed to MIF in the presence or absence of C36L1." (PMID 29875777, 2018). "Specifically, MIF expression in the tumor cells reduces the abundance of activated DCs in the tumor microenvironment, and also suppresses the increase in IFN-gamma producing CD4+ and CD8+ T cells within the tumor." (PMID 29864117, 2018). "Yet for RENCA, tumor progression also yielded an overall increase in suppressive myeloid cell (MDSC) density, as well as increased expression of genes that drive monocytic MDSC immunosuppression (NOS2/iNOS, MIF, and TGFβ2)." (PMID 30388137, 2018). "Also, treatment of PANC-1 cells with the dual covalent tautomerase inhibitor of both MIF and DDT, 4-iodo-6-phenylpyrimidine (4-IPP), reduced proliferation and colony formation in vitro and tumor growth in the mouse xenograft model." (PMID 29707160, 2018). "It is therefore no surprise that MIF is involved in a wide variety of pathologic conditions such as atherosclerosis, sepsis, autoimmunity and tumor survival just to name a few." (PMID 28208600, 2017). "MIF and CD74 were expressed in C2 organoids and in the corresponding tumour tissue." (PMID 28114961, 2017). "A notable feature of this fibrotic microenvironment that warrants further investigation is the elevated presence of macrophage migration inhibitory factor (MIF), a pro-inflammatory cytokine which may also promote tumour angiogenesis and proliferation." (PMID 27999198, 2017). "Several environmental factors, including interleukin-4 (IL-4), tumor-derived transforming growth factor-β (TGFβ), and macrophage migration inhibitory factor (MIF), create a permissive tumor microenvironment for metastasis (TMEM) where the cancer cells intravasate." (PMID 27006653, 2016). "These different results highlight the complex role of MIF and its receptor CD74 in tumor growth." (PMID 26883190, 2016). "Nevertheless, the mechanism of MIF on VEGF is still unclear, and whether it has the same function on VEGF-C so as to influence the formation of tumor lymphatic vessels remains unclear." (PMID 26911617, 2016). "Furthermore, we were able to significantly reduce CAF-cytokine secretion of the tumour cell stimulating cytokines IL 8, IL 13, MCP1, MIF and Serpin E1 by the treatment with Everolimus." (PMID 27206490, 2016). "Although there are a lot of research, reports have revealed MIF takes an important role in cancer development, but the exact mechanism is still not clear, as a new tumor therapeutic target is still full of challenges." (PMID 26911617, 2016). "The 4T1 tumor cell digestions were prepared and surface-stained by the AF405-conjugated F4/80 (AF647-F4/80) antibodies followed by permeabilization and intracellular stain with the AF647-conjugated MIF antibodies." (PMID 25799489, 2015). "Macrophage migration inhibitory factor (MIF) is a pro-inflammatory cytokine that is overexpressed in a number of solid and hematologic malignancies with NSCLC being one of the highest overexpressing tumor types." (PMID 24932684, 2014). "While MIF levels in primary tumours had no bearing on patient outcomes there was a clear indication that high MIF expression levels in metastatic lesions were significantly associated with shorter survival times." (PMID 25168062, 2014). "Since MIF activity requires binding to CD74, we also examined human tumor expression of CD74." (PMID 24887129, 2014).
tumor (continued). "Interestingly, the expressions of MIF and CXCR4 in tumor cells and in TILs were significantly positively correlated (P < 0.05), and the combined MIF and CXCR4 expression in tumor cells was an independent adverse predictive factor for DFS and OS (P < 0.05)." (PMID 23497377, 2013). "Furthermore, the expression of MIF and CXCR4 in tumor cells were independent factors for reduced DFS and OS in metastatic/recurrent ESCC patients (P < 0.05)." (PMID 23497377, 2013). "Therefore, we evaluated the expression of MIF and its receptor CXCR4 protein in tumor cells and TILs of tumor microenvironment in 136 resected ESCC specimens using immunohistochmeistry staining." (PMID 23497377, 2013). "However, the expression pattern of MIF and CXCR4 proteins in tumor microenvironments and their impact on the survival of cancer patients are still unclear." (PMID 23497377, 2013). "In this context, we examined the expression pattern of MIF and CXCR4 in different cell populations in tumor tissues from 136 patients with ESCC, to determine the predictive value of the MIF and CXCR4 expressions in different cell populations within tumor microenvironment of ESCC." (PMID 23497377, 2013). "MIF and CXCR4 levels were measured by immunochemistry in tumor specimens from 136 resected ESCC." (PMID 23497377, 2013). "Therefore, the protein levels of MIF and CXCR4 in diverse cell populations within the tumor microenvironment have different clinically prognostic values in ESCC." (PMID 23497377, 2013). "Interestingly, the MIF and CXCR4 expression levels in tumor cells and in TILs were positively correlated, and the combined expression of MIF and CXCR4 in tumor cells was an adverse independent factor for survivals of ESCC patients." (PMID 23497377, 2013). "Furthermore, the expression levels of MIF and CXCR4 in tumor cells were independent predictive factors for survivals in patients with metastatic/recurrent ESCC." (PMID 23497377, 2013). "Furthermore, the combined expression of MIF and CXCR4 in tumor cells was an independent predictive factor for DFS and OS according to the multivariate Cox model analysis." (PMID 23497377, 2013). "Interestingly, our results showed for the first time that the combined expression of MIF and CXCR4 in tumor cells was also an independent prognostic marker for ESCC patients and was strongly associated with reduced survival." (PMID 23497377, 2013). "According to these findings, it is conceivable that MIF promotes the growth of both tumor tissues and nontumor tissues in the event of wound repair." (PMID 23050964, 2012). "All tumours show positive staining for MIF and negative staining for PTRF, while all normal tissues were negative for MIF and positive for PTRF staining." (PMID 22461895, 2012). "We further demonstrated that knocking down MIF but not IL-8 in the tumor cell line results in failure of T lymphocytes to migrate to contralateral tumor deposits." (PMID 21647415, 2011). "Furthermore, other investigators observed an increase in the level of cytotoxic T lymphocytes following MIF inhibition achieved by using specific antibodies, and the number of apoptotic tumor cells increased following MIF inhibition." (PMID 24281172, 2010). "We noticed a significant positive correlation between MIF levels and hormone receptors (especially PR) and a significant negative correlation between MIF and tumour size." (PMID 19602265, 2009). "One MIF KO mouse died prior to sacrifice at 22 weeks with cancer noted but was excluded from analysis because necrolysis prevented accurate tumor staging." (PMID 17650334, 2007).
tumor (continued). "Moreover, studies about co culture of macrophages with cancer cell lines showed that MIF expression is induced in a JNKII and NF-kB-dependent manner and acts inducing macrophages MMP release, promoting tumoural cells invasively." (PMID 19384429, 2007). "Macrophage Migration Inhibitory Factor (MIF) is a multifunctional cytokine that contributes to inflammation and cancer, promoting tumor growth, progression, and metastasis through modulation of the tumor microenvironment, stimulation of angiogenesis, and regulation of immune responses." (PMID 41898690, 2026). "Furthermore, multiplex immunohistochemistry (mIHC) analysis of three paired pre-/post-treatment ESCC tissues and four additional pre-treatment tumor samples confirmed that MIF-high tumor cells spatially interacted with GC B cells in non-responder tumors." (PMID 41355948, 2026). "Heterogeneous vascular endothelial cellscan secrete molecules such as MIF and APP, which act on macrophagesurface molecules or complexes such as CD74 and CD44, inhibiting macrophagepolarization toward the antitumor M1 phenotype and promoting polarizationtoward the pro-tumor M2 phenotype." (PMID 40834268, 2025). "Although there might be a slight but nonsignificant trend of less total tumors per mouse and tumor sizes after MIF ablation, overall tumor areas were unchanged upon TAM treatment." (PMID 40835826, 2025). "The high levels of MIF in TME may evoke an immunosuppressive form leading to lower NK cell cytotoxicity, as high levels of MIF inhibit the NK cell-activating receptors, thus limiting its tumor cell recognition and killing capability." (PMID 41159021, 2025). "The macrophage migration inhibitory factor (MIF), and its interacting partners CD74 and CD44 were highlighted, recognized for their roles in injury protection, healing promotion, and B cell survival, plays a pervasive role in mediating communications between tumor cells and macrophages." (PMID 40036264, 2025). "However, TLS-absent environment facilitated tumour cell interactions with immune cells through MIF- and galectin-dependent pathways, recruiting immunosuppressive cells." (PMID 39901202, 2025). "Additionally, MIF sustains tumor cell viability through the AKT survival pathway via an autocrine feedback loop, and promotes angiogenesis through HIF1α-dependent signaling or the NFκB–IL8–VEGF axis, as reported in several tumor models." (PMID 40835826, 2025). "Furthermore, the interaction between the MIF pathway and its ligands, CD74/CXCR4, may play a important role in promoting tumor metastasis." (PMID 41127012, 2025). "Specifically, PKM2-induced CXCL1 and MIF produced by tumor cells can bind to CXCR2 and CXCR4 receptors on MDSCs, thereby activating the signaling pathway of MDSCs and triggering cytoskeletal rearrangement, which makes MDSCs chemotactic to the periphery of tumor cells." (PMID 40948745, 2025). "MIF exerts its function of promoting leukocyte recruitment to inflammatory sites by noncognate interaction with the chemokine receptors CXCR2 and CXCR4, and regulates the MIF-stimulated survival of macrophages, B cells, and tumor cells through its receptor cluster of differentiation 74 (CD74)." (PMID 39851524, 2025). "CD74 primarily promotes tumour progression through its signalling function, making it a potential tumour marker or targeted drug target Due to the absence of targeted inhibitors for CD74, the MIF inhibitor ISO‐1 was chosen to inhibit CD74 function by occupying the binding domain of MIF." (PMID 40411322, 2025). "Studies have shown that MIF interacts with CD74 or CXCR2 and CXCR4 receptors, activating signaling pathways such as protein kinase B (AKT), extracellular signal-regulated kinases (ERK), and nuclear factor kappa-B (NF-κB), thereby promoting tumor proliferation, angiogenesis, and metastasis." (PMID 41562084, 2025).
tumor (continued). "In the tumor microenvironment, PKM2 promotes tumor cells to release cytokines and aggregates a large number of MDSCs around tumor cells, PKM2 facilitates the binding of cytokines, such as CXCL1 and MIF, released by tumor cells to the surface receptors CXCR2 or CXCR4 on MDSCs." (PMID 40948745, 2025). "Moreover, in the human SW480 and DLD-1 CRC cell lines, a MIF depletion via siRNA-mediated MIF silencing mainly failed to reduce the migratory capacity of these epithelial tumor cells." (PMID 40835826, 2025). "However, a key challenge in translating MIF inhibition into clinical practice is the current lack of validated drugs that effectively target tumor-relevant MIF functions." (PMID 40835826, 2025). "To further understand if MIF also mediate the transdifferentiation of myeloid cells into apCAFs, we analyzed expression levels of the MIF gene in human HNSCC and normal tissues using the TCGA database, and uncovered significant upregulation in tumor compared to normal tissues." (PMID 39891284, 2025). "Thus, the study of MIF is complicated by the near ubiquitous expression of the cytokine and widespread presence of both its cognate and noncognate receptors across tumor and immune cells." (PMID 40131169, 2025). "MIF may play a significant role in the development of lymphatic metastasis, the construction of microvascular structures, and the expression of VEGF in the tumor tissue." (PMID 38602556, 2024). "Moreover, the statistical findings showed that there was no significant change in serum MIF levels amongst BC patients with various pathological tumor stages (p = 0.69) and nodal status (p = 0.28)." (PMID 38916819, 2024). "In interactions with epithelial cells, the binding of MIF to CD74 and CD44 may affect cell proliferation, migration, and functions in pathological states, such as promoting tumor cell growth and metastasis in the tumor microenvironment." (PMID 38720887, 2024). "Altogether, STINGel demonstrates its indirect antinociceptive impact by reducing the tumor burden through enhancing the presence of M1-like macrophages and N1-like neutrophils and concurrently activating immune response pathways through the upregulation of TNF and MIF signaling pathways." (PMID 38672274, 2024). "Most importantly, independent of the tumor models used, similar immunosuppressive functions related to MIF have been observed, suggesting that MIF could be a potential target for several cancer types." (PMID 36672343, 2023). "The fact that we did not observe tumor-suppressive effects of MIF in chemically induced NMSC could be explained by the choice of our mouse strain." (PMID 37464010, 2023). "IHC staining of tumor and adjacent healthy tissues indicated up-regulation of the VDAC2, CSNK2A2, and MIF genes in tumor tissues, although the expression levels of ODC1 did not change, possibly because of the large differences in the positive signal values between the various samples." (PMID 37231440, 2023). "Moreover, we found that the C4 subpopulation highly expressed cystatin B (CSTB), matrix metalloproteinase 9 (MMP9), chemokine C-C ligand 5 (CCL5), and macrophage migration inhibitory factor (MIF), which have the characteristics of promoting tumor cell migration and invasion." (PMID 37715019, 2023). "In addition, a low HDS may activate the immune microenvironment by inhibiting the MIF signaling pathway in the TME and regulating GPX4 expression in tumor cells." (PMID 37649598, 2023). "Besides MIF, other upregulated immunosuppressive factors in the TME, such as scavenger receptors, have been described to impact cancer immunogenicity leading to cold tumours." (PMID 37454231, 2023). "Cancer cell-derived MIF or COPA potentially dictated the crosstalk with macrophages through CD74-related signaling pathways and, reciprocally, macrophage-secreted granulin (GRN) might send tumor-promoting signals to cancer cells via TNF receptors." (PMID 36198671, 2022). "MIF is a non-cellular component of TME involved in tumor development." (PMID 35842634, 2022).